TTC21A (tetratricopeptide repeat domain 21A)
Description:
Intraflagellar transport (IFT)-associated protein required for spermatogenesis. Required for sperm flagellar formation and intraflagellar transport.
Synonyms: STI2; IFT139A; Thm2; SPGF37
Tractability: No criterion of Open Targets' tractability assessment is met for any kind of drug.
Gene: Protein-coding gene on chromosome 3 (39,107,194 to 39,140,973, forward strand). Ensembl gene ENSG00000168026.
Subcellular location (Human Protein Atlas): Nucleoplasm
Gene Ontology:
Biological process: flagellated sperm motility; spermatid development; intraciliary retrograde transport; protein localization to cilium
Cellular component: intraciliary transport particle A; cilium
Genetic constraint (gnomAD): Loss-of-function variants: 122 observed, 156.73 expected, observed/expected ratio (o/e) 0.78, 90% interval 0.67 to 0.9. The upper end of that interval is the gene's LOEUF score, 0.9, which puts it in group 3 of 6, group 1 being the genes least tolerant of losing a copy. Missense variants: 1,401 observed, 1,655 expected, observed/expected ratio (o/e) 0.85, 90% interval 0.81 to 0.88. Synonymous variants: 575 observed, 643.53 expected, observed/expected ratio (o/e) 0.89, 90% interval 0.83 to 0.96.
Homologues: Orthologues: chimpanzee TTC21A (99% identical), macaque TTC21A (97% identical), dog TTC21A (82% identical), pig TTC21A (82% identical), guinea pig TTC21A (78% identical), rat Ttc21a (78% identical), mouse Ttc21a (77% identical), rabbit TTC21A (69% identical), tropical clawed frog ttc21a (60% identical), Caenorhabditis elegans ift-139 (29% identical), zebrafish ttc21a (4% identical). Paralogues in human: TTC21B (51% identical).
Diseases named in the same sentence as TTC21A in open-access papers:
TTC21A is named in the same sentence as 19 diseases in open-access papers, as found by Europe PMC text mining. Sharing a sentence is not in itself a finding about the gene and the disease. The quoted sentences say what the papers report.
male infertility (4 papers, 2020 to 2023). The inability of the male to effect fertilization of an ovum after a specified period of unprotected intercourse. "TTC21A is a protein-coding gene associated with male infertility, and might involve in reduced motility of spermatozoa and multiple morphological abnormalities of the sperm flagella (MMAF)." (PMID 36406111, 2022). "The male infertility-related variants identified in SPATA3, TTC21A, TERB1, HYDIN, and CCDC155 can be considered additional examples." (PMID 37644014, 2023).
lung adenocarcinoma (2 papers, 2022). A carcinoma that arises from the lung and is characterized by the presence of malignant glandular epithelial cells. "Previous studies reported TTC21A was associated with the prognosis and immune infiltrating level in lung adenocarcinoma (LUAD) and colorectal cancer." (PMID 36406111, 2022). "Increased TTC21A has been found to correlate with favorable prognosis and increased proportion of immune cells in patients with lung adenocarcinoma." (PMID 35906610, 2022). "In addition, a recent study reported high expression of TTC21A predicts favorable prognosis in lung adenocarcinoma." (PMID 36406111, 2022). "However, TTC21A expression was significantly lower in HNSC (Head and Neck Cancer), KICH (Kidney Chromophobe), LUAD (Lung Adenocarcinoma), LUSC (Lung Squamous Cell Carcinoma), THCA (Thyroid Carcinoma) compared with normal tissues." (PMID 36406111, 2022).
ciliopathy (1 paper, 2018). A genetic disorder of the cellular cilia or the cilia anchoring structures, the basal bodies, or of ciliary function. "Among the list of genes, Cfap70 (or Ttc18) caught our attention as the expression levels appeared to be correlated with the ciliary number, just like Ttc21a (Ift139a) as well as Ttc25, which was recently reported as a novel ciliopathy gene." (PMID 30158508, 2018).
clear cell renal cell carcinoma (1 paper, 2022). "The purpose of present study is to explore the role of TTC21A in clear cell renal cell carcinoma." (PMID 36406111, 2022).
tumor (2 papers, 2020 to 2022). "Analysis of ccRCC cohort in TCGA database revealed that TTC21A expression was significantly elevated in tumor tissues compared with adjacent normal tissues." (PMID 36406111, 2022). "The results of analysis indicated that TTC21A correlated with most tumor-infiltrating immune cells in ccRCC." (PMID 36406111, 2022). "In another study, TTC21A expression in lung adenocarcinoma cancer enhanced the infiltration of immune cells into tumor tissue." (PMID 32854198, 2020). "The results of present study could improve the understanding of the role of TTC21A in ccRCC, which make it possible to become a novel biomarker to predict tumor prognosis and immune infiltration for ccRCC patients." (PMID 36406111, 2022). "However, the investigations of TTC21A in tumor progression were limited." (PMID 36406111, 2022).
cancer (1 paper, 2022). A tumor composed of atypical neoplastic, often pleomorphic cells that invade other tissues. "The expression of TTC21A in different types of cancers was evaluated by using TERM database." (PMID 36406111, 2022).
neurodevelopmental disorder (1 paper, 2020). A behavioral and cognitive disorder with onset during the developmental period that involves impaired or aberrant development of intellectual, motor, or social functions. "Other genes, such as GMIP, NEK1, TFPT, CELSR3, and TTC21A, also showed interactions with ASD or other neurodevelopmental disorder-related genes in each gene network in the previous studies." (PMID 33374967, 2020).
TTC21A also shares sentences with these, for which no sentence is quoted: cholangiocarcinoma (1 paper); dysplasia of fibrous (1); head and neck cancer (1); Kidney Chromophobe (1); Lung Squamous Cell Carcinoma (1); Pheochromocytoma and Paraganglioma (1); prion disease (1); prostate adenocarcinoma (1); rectum adenocarcinoma (1); Sepsis (1); Stomach Adenocarcinoma (1); Thyroid Carcinoma (1).